PAX8 (paired box 8)
Diseases named in the same sentence as PAX8 in open-access papers (continued):
Sharing a sentence is not in itself a finding about the gene and the disease.
metastatic carcinoma (9 papers, 2013 to 2025). A carcinoma which has spread from the original site of growth to another anatomic site. "The 21 PAX8-/Calretinin- metastatic cancers were either breast metastasis (n = 4) and the metastasis from gastrointestinal tract (n = 17)." (PMID 23958394, 2013). "If the differential diagnosis of a tumor sampled by needle core biopsy includes a metastatic carcinoma—such as a lung metastasis, then additional markers such as PAX8, TTF-1, and napsin A can be employed with the caveat that none of these markers are 100% specific or sensitive for a given diagnosis." (PMID 25889632, 2015). "The tumor can simulate a metastatic carcinoma; however, the demonstration of thyroglobulin, TTF1, and PAX8 confirms the thyroid follicular origin." (PMID 32632840, 2020). "IHC study results showed positive reaction with CK20 and CDX2 and negative staining with CK7, PAX8, ER, and PR confirmed the colorectal origin of metastatic carcinoma." (PMID 36110333, 2022). "Additionally, positive staining for GATA-3 and GCDFP-15 confirmed the breast origin of the metastatic carcinoma, while negative staining for markers such as PAX-8 and CDX2 helped exclude primary ovarian and gastrointestinal origins, respectively." (PMID 41332036, 2025). "However, PAX8 staining was non-existent in the case of metastatic carcinoma from the kidney and could be ignored." (PMID 30024911, 2018). "To exclude ovarian or pancreatic metastatic cancer, we added markers of ovarian and pancreatic origin, including CK20, CA19-9, CDX-2, Villin and PAX8, all of which were negative." (PMID 36737820, 2023).
neuroendocrine tumors (9 papers, 2013 to 2025). "However, PAX8 is also expressed in other tumors, including thyroid, ovarian surface epithelial, neuroendocrine tumors, and lymphomas." (PMID 38297323, 2024). "Tumors with close to 100% PAX8 negativity for example included carcinomas of the breast and the liver, gastric, prostatic, pancreatic, and pulmonary adenocarcinomas, as well as small cell carcinomas and neuroendocrine tumors of various sites." (PMID 39105782, 2024). "Similarly, Pax8 positivity can be seen in pancreatic well-differentiated neuroendocrine tumors with overlapping cytomorphological features." (PMID 37098593, 2023). "Overall, PAX8 is expressed in primary and metastatic pancreatic well-differentiated neuroendocrine tumors, enabling reliable differentiation between pancreatic and ileal and pulmonary well-differentiated neuroendocrine tumors using immunostaining methods." (PMID 23425942, 2013). "The observation that pancreatic well-differentiated neuroendocrine tumors frequently express PAX8 may be useful for distinguishing pancreatic primary tumors from tumors of other anatomical sites." (PMID 23425942, 2013). "PAX8 confirmed renal origin, while CD117 and chromogranin were negative, excluding chromophobe/oncocytic and neuroendocrine tumors." (PMID 41133530, 2025).
thyroid nodule (9 papers, 2012 to 2025). A small circumscribed mass in the THYROID GLAND that can be of neoplastic growth or non-neoplastic abnormality. "However, 1 patient with a hot thyroid nodule (patient #230) carried a rare c.985C>T (p.Phe329Leu) PAX8 variant previously predicted as benign." (PMID 38194289, 2024). "Furthermore, molecular analysis using the following markers (BRAF V600E, NRAS, HRAS, KRAS, RET/PTC, and PAX8/PPARg) to evaluate preoperative genetic mutations and rearrangements has been shown to have significant diagnostic value in thyroid nodules with indeterminate cytology." (PMID 37732121, 2023). "Recent large prospective studies have emphasized the ability of genetic markers (BRAF, RAS, RET/PTC, and PAX8/PPARγ) and protein markers (galectin-3) to significantly improve and affect the preoperative diagnostic accuracy especially for patients who have indeterminate thyroid nodules." (PMID 23326756, 2012). "The latest guidelines also suggest (recommendation rating: C) the use of molecular markers (e.g., BRAF, RAS, RET/PTC, and PAX8-PPAR) in the management of thyroid nodules with indeterminate cytology." (PMID 26693224, 2015). "Therefore, the targets widely recognized and recommended by scholars at home and abroad were selected to compose a 6-gene test panel for thyroid nodule diagnosis, including BRAF V600E mutation, TERT mutation, and gene fusions (CCDC6-RET, NCOA4-RET, ETV6-NTRK3, EML4-NTRK3, STRN-ALK, and PAX8/PPARG)." (PMID 40586006, 2025).
Wilms tumor (9 papers, 2011 to 2024). An embryonal neoplasm characterized by the presence of epithelial, mesenchymal, and blastema components. "One study showed that PAX8 was expressed in over 80% of Wilms tumor cases by immunohistochemistry, while PAX2 was present in over 90% of cases (n = 45)." (PMID 38473380, 2024). "Altered expression of PAX8 is described in Wilms tumor, ovarian, uterine, renal, and prostatic malignancies, making it a clinically useful tumor marker." (PMID 39639036, 2024). "The current study demonstrated PAX2 expression in 91.1% of Wilms tumor cases and PAX8 expression in 82.2% of cases." (PMID 34306127, 2021). "This study aimed to evaluate the expression of PAX2 and PAX8 in Wilms tumor using immunohistochemical methods (IHC)." (PMID 34306127, 2021). "As in the current study, the results of these studies indicate a high frequency of PAX2 and PAX8 expression in Wilms tumor, making these markers sensitive markers for diagnosing this tumor." (PMID 34306127, 2021). "This study aimed to investigate the immunohistochemical expression of PAX2 and PAX8 in Wilms tumor for diagnosing this tumor and possibly differentiating it from other differentials." (PMID 34306127, 2021). "For the decreased genes the biggest overlap was found in the intersection between the Nes-Cre Wt1 conditional and both sets of Wilms' tumour datasets (9 genes) or the Pax8+/CreWt1 conditional and both tumour sets (18 genes)." (PMID 26035382, 2015). "PAX2 and PAX8 expressions are also commonly detected in Wilms tumor, a pediatric kidney tumor." (PMID 38473380, 2024). "Markers such as WT1, which is typically positive in Wilms’ tumor (in addition to PAX8, CD56, and CD57), help confirm a nephroblastic origin, while others like cytokeratins, desmin, and S-100 protein assist in identifying the specific tissue types within a tumor." (PMID 39596492, 2024). "This study aimed to investigate the IHC expression of PAX2 and PAX8 in Wilms tumor." (PMID 34306127, 2021). "The third component was represented by TTF1+/PAX8+ primitive teratoid epithelial tubules reminiscent of primitive thyroid follicles and/or Wilms tumor, admixed with scattered respiratory- or enteric-type tubules, neuroepithelial rosettes, and fetal-type squamoid nests." (PMID 32507920, 2020). "This comparison showed a close resemblance between the Nes-Cre Wt1co mutants and the WT1-mutant tumours, especially with respect to the ectopic muscle development signature, whereas the phenotype in the Pax8+/CreWt1co mutant kidneys more resembled the one found in WT1-wild-type Wilms' tumours." (PMID 26035382, 2015). "Notably, the Wilms tumor metastasis (post-treatment) contained prominent fibrous stroma entrapping an admixture of native respiratory epithelium as well as minute glands, positive for PAX8, negative with TTF1, indicating neoplastic epithelial origin." (PMID 32193604, 2020). "Wilms tumor can be differentiated from MA in staining as it is positive for WT1 and PAX8 and negative for vimentin and CD57." (PMID 38957819, 2024). "Finally, GO terms related to kidney development (grey nodes) are found for the Pax8+/CreWt1co/co kidneys and the WT1-wild-type Wilms' tumours but not in the Nes-Cre Wt1co/co and WT1-mutant Wilms' tumour samples, consistent with an early, pre-MET, origin of these tumours." (PMID 26035382, 2015).
mucinous carcinomas (8 papers, 2014 to 2025). "However, since the majority of POSRCC cases are admixed with mucinous adenocarcinoma, the diagnostic value of PAX8 for differentiating POSRCC from metastatic ovarian carcinoma is limited." (PMID 41517393, 2025). "PAX8 and C-KIT were upregulated in most tumor types, while CKAP4 and DUSP1 were upregulated only in serous and mucinous adenocarcinoma." (PMID 31159852, 2019). "In a similar manner, in the HMucBOT-2 tumor, mucinous carcinoma lesions expressed all of these markers, with undifferentiated lesions exhibiting PAX8 expression but not CK7 or MUC1 expression." (PMID 40427213, 2025). "Mucinous carcinoma PDOs presented with diffuse CK7 positive, focal PAX8 positive, and CK20 negative, matching the parent tumors and reference data." (PMID 39358778, 2024). "PAX8 was expressed in all LGSC, in 87% of HGSC and in none of the mucinous carcinomas." (PMID 32677969, 2020).
squamous cell carcinoma (8 papers, 2014 to 2025). A carcinoma arising from squamous epithelial cells. "This case highlights the effectiveness of PAX-8 stain in determining the primary site of tumour when squamous cell carcinoma is found in both lung and thyroid gland." (PMID 31772786, 2019). "The intensity of PAX8 expression increased from squamous cell carcinoma to large cell carcinoma to adenocarcinoma." (PMID 24628993, 2014). "Relative levels of PAX8 protein were elevated (≥ + 2 on a scale of 0–3) in adenocarcinoma (58/94), large cell carcinoma (50/85), squamous cell carcinoma (28/47), and metastatic NSCLC (17/28; lymph node)." (PMID 24628993, 2014). "The 47 squamous cell carcinoma tissues examined, however, were all positive for PAX8 protein expression." (PMID 24628993, 2014). "Notably, monoclonal PAX8 and CD5 antibodies are useful in differentiating ITTC from poorly differentiated thyroid carcinoma (PDTC) and squamous cell carcinoma (SCC)." (PMID 41476594, 2025). "It has been reported that PAX-8 is positive in PSCCT, whereas squamous cell carcinomas from the cervix, esophagus, and lung were negative for PAX-8." (PMID 36329478, 2022).
gynecological cancers (7 papers, 2012 to 2026). "Importantly, we define a PAX8–MECOM gene signature that characterizes patients of gynecological cancers with poor prognosis." (PMID 33903593, 2021). "This gene module correlates with PAX8 and MECOM expression in large scale profiling of cell lines, patient-derived xenografts (PDXs) and clinical cases and stratifies gynecological cancer cases with worse prognosis." (PMID 33903593, 2021). "In both CK7 + /CK20 − /ER + (1 case) and CK7 + /CK20 + /ER + (2 cases) adenocarcinomas, PAX8/WT1 expression was performed to rule out gynecological cancers." (PMID 36346458, 2023).
hepatocellular carcinoma (7 papers, 2016 to 2024). A malignant tumor that arises from hepatocytes. "Paired-box family member PAX8 encodes a transcription factor that has a role in cell differentiation and cell growth and may participate in the prognosis of hepatocellular carcinoma (HCC)." (PMID 28339471, 2017). "Liver lipidomic profiling revealed oleic acid was enriched in Pax8 +/- mice consistent with a previous study demonstrating that increased intake of this fatty acid promotes hepatoma progression by reducing the expression of Pten." (PMID 31518338, 2019). "Necropsy revealed that Pax8 +/- mice were susceptible to develop with age liver cancers with hallmarks of hepatocellular carcinoma, as no gross anatomical alterations were detected at day 21 of life." (PMID 31518338, 2019).
malignant mesothelioma (7 papers, 2013 to 2025). A malignant neoplasm of the pleura or peritoneum, arising from mesothelial cells. "The immunohistochemical expression of PAX8 (Paired box gene 8) in ovarian-type epithelial tumours is also a very valuable tool for the distinction as it is only rarely traceable in malignant mesothelioma." (PMID 26197800, 2015). "The 2 cases showing PAX8-/Calretinin + turned out to be malignant mesothelioma." (PMID 23958394, 2013). "More organ-specific antibodies will be added such as ER, PR, PAX8 (Müllerian tumours), TTF1 (lung, thyroid), GATA3 (breast, urothelial), CDX2 (gastrointestinal) and Calretinin, BerEP4, WT1 and CK5/6 (malignant mesothelioma)." (PMID 29621151, 2018). "Conversely, both mesothelial cells and mesothelioma show PAX8 negative expression, so that PAX8 staining reliably distinguishes ovarian serous tumors from malignant mesotheliomas." (PMID 35055018, 2022). "PAX8 is a useful marker to distinguish gynaecologic carcinomas from non-gynaecologic malignancies including malignant mesotheliomas, cancers of gastrointestinal origin and breast carcinomas CK7+/CK20− and hormone receptor-positive." (PMID 29621151, 2018). "Recent studies showed that PAX8 is a useful marker to distinguish gynecologic cancers from non-gynecologic malignancies including malignant mesotheliomas, cancers of gastrointestinal origin and breast cancers, which are common confusion sources in clinicopathological practice." (PMID 23958394, 2013).
medullary thyroid carcinoma (7 papers, 2014 to 2024). "The PAX8 positivity rates of 0–75% reported earlier for medullary carcinomas of the thyroid may to some extent be caused by PAX8 antibodies cross-reacting with PAX6." (PMID 39105782, 2024). "PAX8 expression in medullary thyroid carcinoma depends on the antibody used." (PMID 32632840, 2020). "Histologic preparations should be reevaluated by IHC to guide the search for the primary tumor: TTF-1 (pulmonary or medullary thyroid carcinoma), CDX-2 (intestinal), PAX-8, histidine-decarboxylase (pancreatic), xenin (duodenal), gastrin (occult gastrinoma), and PP/glucagon (pancreatic)." (PMID 25038902, 2014). "Moreover, practicing pathologist should also be aware that medullary thyroid carcinomas can express PAX8 in a clone-dependent manner, in which absence of immunoreactivity is noted when monoclonal PAX8 antibodies are applied, as opposed to positive staining using polyclonal antibodies." (PMID 33269427, 2021).
ovarian serous tumor (7 papers, 2013 to 2024). A benign, borderline, or malignant epithelial tumor of the ovary characterized by the presence of neoplastic epithelial cells that, in well differentiated tumors, resemble the epithelial cells of the fallopian tube and, in poorly differentiated tumors, show anaplastic features. "Furthermore, we stained tumors for expression of PAX8, an established marker of high-grade serous ovarian tumors." (PMID 24020521, 2013). "PAX8 is expressed in ovarian and endometrial neoplasias, whereas WT1 is expressed in ovarian serous tumors and is useful to support ovarian origin." (PMID 31807285, 2019). "HGSOCs bear morphological resemblance to Müllerian epithelia and over 80% of this tumor type overexpress PAX8, an FTSEC marker that can be used to distinguish ovarian serous tumors from other, morphologically similar neoplasms." (PMID 24070420, 2013).
prostate carcinoma (7 papers, 2012 to 2022). A carcinoma that arises from epithelial cells of the prostate gland. "PAX8 staining can aid in differentiating these tumors from other male genitourinary tumors that are PAX8-negative, such as urinary tract, testicular, and prostate cancer." (PMID 35806410, 2022).
carcinosarcoma (6 papers, 2019 to 2025). A malignant tumor composed of a mixture of carcinomatous and sarcomatous elements. "The carcinomatous components in all 7 carcinosarcomas showed PAX8 nuclear expression in keeping with Mullerian epithelial differentiation." (PMID 41202566, 2025). "On the other hand, PAX8 was mainly positive in epithelial components in parental tissues of carcinosarcomas, and the proportions of PAX8-positive cells were increased in the PDX for two cases (UXE-004 and -005) and negatively converted in the PDX for another case (UXE-008)." (PMID 37231035, 2023). "PAX8 and CK7 were never diffusely positive, although the epithelial component of coexisting carcinosarcoma in two cases stained diffusely with PAX8 and CK7." (PMID 34977100, 2021).
colorectal carcinoma (6 papers, 2016 to 2024). A malignant epithelial neoplasm that arises from the colon or rectum and invades through the muscularis mucosa into the submucosa. "We used RT-qPCR to determine the relative expression levels of four paired box (PAX) genes which are most likely to encode binding targets for EG1 in colorectal carcinoma cells (PAX2, PAX5, PAX6, PAX8)." (PMID 34722257, 2021). "PAX8, noted for its limited expression in ovarian tissue, is weakly and focally expressed in about 35% of MOC cases, contrasting with its 5% expression in appendiceal cancers and absence in colorectal cancers." (PMID 39040449, 2024).